MB (myoglobin)
Diseases named in the same sentence as MB in open-access papers (continued):
Sharing a sentence is not in itself a finding about the gene and the disease.
ischemia (21 papers, 2011 to 2025). A hypoperfusion of the BLOOD through an organ or tissue caused by a PATHOLOGIC CONSTRICTION or obstruction of its BLOOD VESSELS, or an absence of BLOOD CIRCULATION. "In this study, we demonstrated that the fluorescence spectrum of myoglobin encodes for the oxidation–reduction state of the myocardium following ischemia–reperfusion and that this signal could be used to quantify very early the infarct size in cleared mouse hearts." (PMID 38499702, 2024). "Although SGLT2 is rarely present in cardiomyocytes, acute systemic administration of dapagliflozin prior to ischemia significantly suppressed myocardial myoglobin efflux during myocardial I/R possibly due to a systemic effect." (PMID 39014025, 2024). "First, several studies have illustrated multiple pathologic factors, such as ischemia, compression and thrombosis result in rhabdomyolysis and release myoglobin." (PMID 35273980, 2022). "Its blood levels start to increase within the first 30 min to 2 h after the onset of ischemia, which makes myoglobin an important marker for the early detection/exclusion of cardiac injury." (PMID 34063483, 2021). "During high-intensity exercise hemoglobin and myoglobin deoxygenate, with this effect exacerbated in ischemia." (PMID 31661850, 2019). "During high-intensity exercise as well as during ischemia, nitric oxide (NO) is produced in skeletal muscle from nitrite by the action of nitrite reductases such as myoglobin, deoxyhemoglobin and XO." (PMID 30736383, 2019). "Reportedly, changes in hemoglobin/myoglobin oxygen desaturation between rest and exercise, expressed relatively to maximal oxygen desaturation determined with cuff ischemia, are greater during GS (79.2%) than SL (65.7%)." (PMID 30140231, 2018). "Furthermore, the results suggest that tissue oxygenation has a major impact on the amounts of sequestered versus unbound long chain fatty acids associated with myoglobin, which could have important implications for modifying myocyte fuel partitioning during ischemia or intense exercise." (PMID 26030763, 2015). "Mild positivity of immunoreaction (tryptase, CD15, IL-1β, IL-6, IL-8, TNF-α) and stronger reactivity for IL-15, MCP-1 in areas where depletion of cellular antigens (myoglobin and cardiac troponin) is detectable within 30 – 40 minutes from ischemia." (PMID 24989171, 2014). "If cases with somewhat milder ischemia and longer duration (12-36 h) are excluded, patients had a mean myoglobin level >11 000 ng/ml." (PMID 24170993, 2013). "Optical spectra become broader with a more pronounced peak at 760 nm as hemoglobin and myoglobin transition from their oxygenated to deoxygenated states during ischemia." (PMID 22132085, 2011). "It is arterial in nature because a higher increase in oxyhemoglobin and oxymyoglobin could be measured in the tissue compared to the decrease in deoxyhemoglobin and myoglobin during recovery from ischemia." (PMID 36079169, 2022). "Thus some caution must be employed when interpreting data obtained within the first 10 s or so of ischemia or reperfusion, when the major changes in myoglobin oxygenation state and thus internal filtering occur." (PMID 27907091, 2016). "Therefore, myoglobin collected during ischemia may represent structural damage around the dialysis fiber." (PMID 39014025, 2024). "The lack of a significant difference in serum myoglobin levels shows that the degree of myocardial injury appears to be dominated by ischemia, not mechanical trauma in our setting." (PMID 25886909, 2015). "During ischemia, the movement of high-molecular-weight molecules such as myoglobin may be limited because of the lack of blood flow in the ischemic region." (PMID 39014025, 2024). "In conclusion preoperative topical hypothermia protected the limb muscles against serious ischemia in terms of serum myoglobin dynamics and muscular function, and may be a promising way to treat patients with TASC class IIb/III ischemia pending revascularization." (PMID 24170993, 2013).
Hyperkalemia (19 papers, 2009 to 2026). An abnormally increased potassium concentration in the blood. "CS patients may present with dehydration; coagulation disorders; elevated creatine phosphokinase and myoglobin levels; hyperkalemia and hypocalcaemia, which may cause life-threatening arrhythmias and therefore need urgent and aggressive therapy." (PMID 20606796, 2010). "Laboratory studies revealed extreme elevations in creatine kinase (peak CK 22,476 U/L), myoglobin (3,852 ng/mL), and lactate dehydrogenase, alongside hyperkalemia and hypocalcemia." (PMID 42026529, 2026). "The release of large amounts of myoglobin and electrolytes increases the risk of AKI, hyperkalemia, and arrhythmias, predisposing to cardiac events and multiorgan failure." (PMID 41200632, 2025). "Rhabdomyolysis, the breakdown of muscle tissue, releases potassium into the bloodstream, leading to hyperkalemia; it also releases toxic substances like myoglobin, which can result in multi-organ failure, with AKI being the most serious complication." (PMID 39759753, 2024). "Clinical or biochemical evidence of rhabdomyolysis (increased postoperative levels of CK and myoglobin, myoglobinuria, hyperkalemia) is also highly suspicious for MH." (PMID 36360420, 2022). "The impaired kidney blood perfusion, intratubular obstruction by myoglobin, and severe hyperkalemia are the major factors that contribute to the pathogenesis." (PMID 31319855, 2019). "They include critically ill hypercatabolic patients (e.g., burn injury or tumor lysis syndrome), patients who need an urgent correction of severe hyperkalemia or metabolic acidemia, and rhabdomyolysis patients in whom myoglobin should be rapidly removed." (PMID 30909778, 2019). "Loss of intracellular electrolytes (potassium, magnesium, phosphate) ensues followed by leaking out of myoglobin and creatine kinase leading to hyperkalemia and other dyselectrolytemia." (PMID 31065209, 2019). "‘Crush syndrome’ is an umbrella term that describes AKI (Cr and Urea both significantly elevated and myoglobin present in the urine) with hyperkalemia following extensive muscle death." (PMID 25881255, 2015). "In addition to increased amounts of serum CK, other biochemical abnormalities include elevated transaminases, LDH and myoglobin, myoglobinuria, and electrolyte or acid–base disturbances, such as hyperkalemia, hyperphosphatemia, hypocalcemia, hyperuricemia, and metabolic acidosis." (PMID 32729460, 2020). "The timing of initiating dialysis is a challenge and should not be determined solely by myoglobin or CK serum concentration but by the status of renal impairment, with complications such as life-threatening hyperkalemia, hypercalcemia, hyperazotemia, anuria, or hyperhydration without response." (PMID 29109879, 2017).
Sepsis (18 papers, 2011 to 2025). Sepsis is defined as life-threatening organ dysfunction caused by a dysregulated host response to infection. "Our previous retrospective study showed that myoglobin elevation 14 days after ICU admission was an independent risk factor for death in patients with sepsis-induced chronic critical illness." (PMID 38264034, 2023). "And age, female, myoglobin and virus-positive results were independent risk factors for sepsis." (PMID 35909965, 2022). "Thus, it is quite possible that myoglobin deficiency may damage intramuscular metabolism during the post‐sepsis phase." (PMID 39016179, 2024). "In a study of 211 sepsis patients, serum myoglobin was positively correlated with ICU-AW severity and mortality, with levels > 1362.5 ng/ml indicating an increased risk (AUC 0.843, 95% CI: 0.819–0.867)." (PMID 40601169, 2025). "In our previous retrospective study, 131 patients with sepsis were divided into the myoglobin rise group and the myoglobin fall group according to the myoglobin levels on the first and 14th days." (PMID 38264034, 2023). "Cytokine adsorber (CytoSorb) has been used successfully as adjunctive treatment for adult patients with elevated cytokine levels in the setting with severe sepsis and septic shock and to reduce blood myoglobin, unconjugated bilirubin, and conjugated bilirubin." (PMID 28127473, 2017). "Its applications include sepsis and septic shock through the removal of inflammatory cytokines; hepatic failure by eliminating bilirubin and ammonia; rhabdomyolysis by removing myoglobin; and the rapid elimination of anticoagulant drugs like ticagrelor and rivaroxaban." (PMID 40724567, 2025). "Admission serum myoglobin and CK levels were significantly associated with HVI, TBSA, BICU length of stay (LOS), ventilator days, number of interventions, mortality, amputation, flap surgery, RRT, and sepsis (p < 0.001)." (PMID 29855384, 2018). "While the present trial focuses on dampening chronic inflammation in dialysis patients, the results also suggest MCO-Ci dialysis as a treatment option for other disease entities demanding removal of solutes in this molecular size range such as free light chains, myoglobin, and cytokines in sepsis." (PMID 28085888, 2017). "HP was found to be a reliable marker for the development of secondary sepsis, which is based on upregulation of the heme degradation pathway by free heme after allogenic blood transfusion or release of myoglobin from traumatic tissue damage, as implied by a most recent study." (PMID 26607226, 2015). "In the RMST regression, after adjustment for age, sepsis, SOFA score, and other confounders, the increase in myoglobin level was still significantly related to the decrease in the survival time." (PMID 38264034, 2023). "Age, sequential sepsis-related organ failure score (SOFA), serum myoglobin (MYO), vasopressor use, and mechanical ventilation were identified as independent risk factors for 1-year mortality in the nomogram predictive model." (PMID 35573024, 2022). "Admission CK and myoglobin levels correlated significantly with HVI, burn size, ventilator days, surgical interventions, amputation, flap surgery, renal replacement therapy, sepsis, and mortality." (PMID 29855384, 2018). "In a prospective study of 19 patients with severe sepsis or septic shock and 12 patients with hypovolemic shock, markers of myocardial injury were studied (cTnI, CK, CKMB and myoglobin)." (PMID 22758615, 2011). "The level of CK-MM was significantly higher in sepsis group, but there were no significance between CK, CK-MB, and myoglobin." (PMID 35363162, 2022).
heart failure (16 papers, 2012 to 2025). Inability of the heart to pump blood at an adequate rate to meet tissue metabolic requirements. "Men with myocarditis have been found to have higher levels of heart failure biomarkers, creatine kinase, myoglobin, and T helper 17–associated cytokines." (PMID 38206659, 2024). "Deficiency of myoglobin, even accompanied by a transient increase in NO• (i.e., under the condition of iNOS-induced nitrosative stress), resulted in cardiac hypertrophy and development of heart failure." (PMID 35269826, 2022). "However, double mutants with cardiomyocyte-specific overexpression and concomitant myoglobin deficiency (iNOS+/+/myo−/−) developed definitive sign of heart failure." (PMID 22905206, 2012). "Men with myocarditis have been found to have higher levels of heart failure biomarkers soluble ST2, creatine kinase, myoglobin and T helper 17-associated cytokines while women develop a better regulatory immune response." (PMID 36937911, 2023). "Among these biochemical data indicating myocardial necrosis and heart failure, myoglobin and NT-proBNP were significantly elevated in AMI patients with poor prognosis." (PMID 32903533, 2020). "Heart failure-related parameter myoglobin, inflammatory parameters CRP and LDH were much higher in severe subgroup." (PMID 32695551, 2020). "Cardiac biomarkers troponin I, myoglobin and NT-proBNP demonstrated presence of myocardial injury and heart failure, especially in chronic infections, which in some cases, slightly improve after the adulticide treatment." (PMID 29143665, 2017). "It is suggested that myoglobin is increased to different degrees in each stage of heart failure." (PMID 36855100, 2023). "Myoglobin can reflect the severity of heart failure and predict the prognosis of patients." (PMID 36855100, 2023). "Besides impairing oxygen supply through blocking Hb, CO might theoretically exert detrimental effects in heart failure patients by binding to myoglobin." (PMID 30483155, 2018). "Thus, one of the reasons for the slower decline of recovery, oxygen uptake in patients with heart failure seems to be the impaired ability of the circulatory system to deliver rapidly the amount of oxygen needed for replenishment of myoglobin in the peripheral muscles." (PMID 22312564, 2012). "The evaluation of cardiac markers revealed their reaction, suggestive of myocardial injury and heart failure, as follows: CKMB: 7.6 mg/mL; Myoglobin: 207 mg/mL; Troponin: 1.64 mg/dL; BNP: 2490 pg/mL; and D-dimer: 3300 mg/mL." (PMID 39860409, 2025). "As several genes (MB, DJ-1, and GSN) identified via quantitative proteomics are also involved in heart failure following MI18, 19, 20, we examined whether WE intake could modulate pathological LV remodelling after MI." (PMID 27929093, 2016). "The AFFIRM-AHF trial suggests that the reduction in hospitalisations for heart failure is not observed until 8–12 weeks after administration of IV iron, consistent with its benefits being mediated through the synthesis of new red blood cells, myoglobin and other metalloproteins." (PMID 33755777, 2021).
myocardial ischemia (16 papers, 2009 to 2025). A disorder of cardiac function caused by insufficient blood flow to the muscle tissue of the heart. "The objective of our study is to verify if PON1 55 polymorphism is associated with risk of acute coronary syndrome (ACS) and with biochemical myocardial ischemia markers, such as troponin I, creatine kinase (CK)-MB, myoglobin, and C-reactive protein." (PMID 22536511, 2012). "Recent studies on the postmortem diagnosis of myocardial ischemia have immunohistochemically examined markers that either accumulate (such as fibronectin) or leak (such as troponin, myoglobin, and S100A1) into human myocytes during ischemic injury." (PMID 38374168, 2024). "The cardioprotective effect of ultrasound targeted hs-MB destruction was investigated in a rodent model of myocardial ischemia-reperfusion injury." (PMID 27469291, 2016). "We then assessed the mean plasma levels of C-reactive protein and myocardial ischemia markers (troponin I, CK-MB, and myoglobin) according to the PON1 55 carriers." (PMID 22536511, 2012). "Our study showed that myoglobin was significantly higher in the low mDBP24h group, suggesting that low DBP may be associated with myocardial ischemia." (PMID 37689707, 2023). "These comparative analyses revealed that cellular proteins such as troponins, myoglobin, and connexin 43 showed an earlier alteration of the regular expression than C5b-9 deposition, suggesting remarkable usefulness for the diagnosis of early myocardial ischemia." (PMID 33147886, 2020).
Hypertension (15 papers, 2017 to 2024). The presence of chronic increased pressure in the systemic arterial system. "Serum creatine kinase-MB isoenzyme activity, troponin I, and lipid profile were evaluated in 140 male and 100 female Nigerians with hypertension." (PMID 29099024, 2017). "We retrospectively enrolled subjects with PA and essential hypertension (EH) who had completed testing for serum high sensitivity troponin T (hs-TnT), creatine kinase isoenzyme MB (CK-MB) and myoglobin from the database of the Chongqing Primary Aldosteronism Study (CONPASS)." (PMID 35265036, 2022). "Meanwhile, age, male, history of hypertension (HP), myoglobin (MYO), creatine kinase-MB (CK-MB), high-sensitivity troponin-I (Hs-TnI), urea, creatinine, white blood cell (WBC), lymphocytes (LYM), c-reactive protein (CRP) and procalcitonin (PCT) were correlated with the risk of in-hospital death." (PMID 32293449, 2020). "When we compared by high blood pressure group in pregnancy, there were significant differences in mean arterial pressure (MAP), platelet count, ALT, AST, troponin, myoglobin, sFlt-1 MoMs, and sFlt/PlGF ratio." (PMID 35615097, 2022). "Participants with hypertensions had increased circulating myoglobin (p = 0.02) and LCN2/NGAL (p = 0.02), but no changes in VCAM-1 (p = 0.15) or platelets (p = 0.30)." (PMID 37598150, 2023). "None of the three markers (hs-TnT, CK-MB and myoglobin) were significantly associated with SBP, DBP, duration of hypertension, serum creatinine concentration, serum potassium concentration, plasma aldosterone concentration or ARR in the EH group (p>0.05)." (PMID 35265036, 2022). "Age, pre-existing conditions (cardiac disease, hypertension, and more than two comorbidities), and 1st Laboratory detection (WBC, NEU, LYM%, NEU%, NLR, FIB, CRP, TBIL, ALB, GRF, CK-MB, Myoglobin, and Troponin) were identified as the predictors of the severity of disease by univariate analysis." (PMID 32582575, 2020).